TNF (tumor necrosis factor)
Diseases named in the same sentence as TNF in open-access papers (continued):
Sharing a sentence is not in itself a finding about the gene and the disease.
depression (continued). "The overproduction of pro-inflammatory cytokines, such as tumor necrosis factor-alpha and interleukin-6, has been observed in cases of depression." (PMID 38424581, 2024). "Neutrophils can secrete inflammatory mediators, such as IL-6 and TNF-α, which can damage the brain’s neurotransmitter system and worsen the symptoms of depression." (PMID 39655209, 2024). "Clinical studies have shown that the levels of IL-1, IL-6, TNF-α, and IFN-α are generally elevated in SS patients; therefore, some people believe that SS is a cause of depression and anxiety." (PMID 39479595, 2024). "Taken together, these results showed that TNF-α overexpression promoted the development of depression." (PMID 38710713, 2024). "ROC curve analysis demonstrated that IL-1α, IL-6, and TNF-α showed high accuracy in discriminating patients with severe depression." (PMID 39595067, 2024). "Studies consistently demonstrate elevated levels of pro-inflammatory cytokines, such as interleukin-6 (IL-6) and tumour necrosis factor alpha (TNF-α), in the brains and blood of individuals with PD and depression." (PMID 38337395, 2024). "Inflammatory cytokines are increased in depressed patients and mouse models of depression, and TNF-α and IL-6 expression is elevated in the prefrontal cortex and orbitofrontal cortex of depressed patients who die by suicide." (PMID 38902845, 2024). "It has been shown that patients with major depressive disorders had increased inflammatory markers such as interleukin (IL)-1β, IL-6, tumor necrosis factor (TNF)-α and C-reactive protein (CRP)." (PMID 39394060, 2024). "Since then, many studies have demonstrated increased levels of acute-phase proteins and pro-inflammatory cytokines such as C-reactive protein (CRP), IL-1, IL-1β, IL-6 and TNF-α in depression." (PMID 38575920, 2024). "To further demonstrate the role of TNF-α in depression, we injected infliximab (Inf), a TNF-neutralizing antibody, into the cerebrospinal fluid of mice." (PMID 38710713, 2024). "Inflammatory markers, such as C-reactive protein, tumor necrosis factor-α, and interleukin-6, were elevated in both depression and migraine." (PMID 38881795, 2024). "To further identify the mechanism of TNF-α during depression, we used CUMS mice as our in vivo experimental model." (PMID 38710713, 2024). "People who suffer from depression have increased concentrations of inflammatory state markers, such as interleukin 6 (IL-6), tumor necrosis factor-alpha (TNF-α), and other interleukins, while interferon-gamma (IFN-γ) levels are decreased." (PMID 38732635, 2024). "IL-10 expression was inhibited in the CUMS model, and increased levels of IL-1β, IL-6, and TNF-α were observed in the sera of the CUMS mice with depression-like behaviors." (PMID 38378622, 2024). "According to a recent meta-analysis of cytokines in major depression, the proinflammatory cytokines IL-6 and TNF-α were significantly increased in depressed subjects when compared to healthy controls." (PMID 38674048, 2024). "In the case of the rapid-acting antidepressant ketamine, a randomized trial showed a rapid decrease in TNF-α levels following ketamine infusion, which also correlated to the alleviation in depression severity." (PMID 38673781, 2024). "Increased IL-6 and TNF-α have been reported in depressive patients and are positively correlated with Hamilton Depression Scale-17." (PMID 38999797, 2024). "A meta-analysis on a total sample of 10,249 individuals revealed that the mean levels of seven inflammatory markers, including IL-6 and TNF-α, were elevated in patients with depression in comparison to healthy controls." (PMID 39273621, 2024). "The results highlighted that IL-6 (AUC = 0.724; 95% CI: 0.648–0.801) and TNF-α (AUC = 0.861; 95% CI: 0.797–0.925) are significant predictors for major depressive disorder." (PMID 39595067, 2024).
depression (continued). "It has been shown that pro-inflammatory cytokines such as interleukin-1β (IL-1β) and tumor necrosis factor (TNF) can activate systemic inflammatory responses, directly or indirectly mediating the onset of depression." (PMID 39367470, 2024). "The main effects of the diagnosis condition (bipolar disorder vs major depressive disorder vs control group) were noted on the mean time (P = .045) and the SD of mean time (P = .013), as well as the TNF-α levels (P < .001)." (PMID 39283831, 2024). "The rat depression model is accompanied by increased TNF expression in the brain tissue, leading to nerve cell necrosis." (PMID 39639753, 2024). "To confirm the presence of inflammation in rats with MI and depression, we quantified the levels of IL‐1β, IL‐18, and TNF‐α in rat serum using ELISA." (PMID 38970230, 2024). "The results of the study showed that SNPs of eNOS, HSP70, FKBP5, miR-146a, ACE2, MAS1, SGK1, IL-4–589, IL-6–174, TNF-α–308, CRP–717, 5-HTTLPR, and BDNF genes are associated with the comorbidity of coronary heart disease and depression." (PMID 38745947, 2024). "Subsequent studies reveal that individuals with depression often exhibit elevated levels of tumor necrosis factor‐alpha (TNF‐α) and other inflammatory factors." (PMID 39639753, 2024). "TNF-α, IL-1β and IL-6 promote depression and inhibit the functional activity of serotonergic neurons." (PMID 38898454, 2024). "In patients with depression, levels of interleukin (IL)-6 and tumor necrosis factor (TNF) are significantly increased in blood and cerebrospinal fluid." (PMID 39200183, 2024). "Individuals with depression, for instance, frequently show elevated levels of pro-inflammatory cytokines—such as IL-1β, IL-6, and TNF-α—in their blood and cerebrospinal fluid." (PMID 39273641, 2024). "EE also decreased stress-induced visceral pain and anxiety/depression-like phenotypes, while upregulating expression of IL-10 and downregulating expression of TNFα and IL-1β in specific parts of the mouse brain." (PMID 38256537, 2024). "Several studies have reported that patients with depression exhibit significantly elevated levels of pro‐inflammatory cytokines, including TNF‐α, IL‐1β, and IL‐6." (PMID 39554370, 2024). "Patients initiating TNF inhibitors also had a lower prevalence of comorbidities, except liver disease and depression, and had higher white blood cell counts and eGFR levels and lower serum albumin levels." (PMID 38625700, 2024). "A 6-week longitudinal study conducted back in 2010 investigated the impact of TNF-α antagonist therapy on depression, anxiety, and quality of life (QoL) in AS patients." (PMID 38571822, 2024). "Ferulic acid inhibited the activation of microglia and significantly decreased the contents of IL-1β, IL-6, and TNF-α in the prefrontal cortex of the CUMS-induced depression mouse model by inhibiting the NLRP3/caspase-1/NF-κB pathway." (PMID 38915473, 2024). "Depression and inflammation exhibit a bidirectional relationship: depression can promote an inflammatory response, and conversely, blocking pro-inflammatory factors (e.g., TNF-α) can partially alleviate depressive symptoms." (PMID 38404466, 2024). "SC therapy can significantly reduce the expression levels of proinflammatory factors such as IL-6, IL-1, and TNF-α in the serum of patients with depression and upregulate anti-inflammatory factors to improve the brain inflammatory response." (PMID 39654612, 2024). "Inflammatory cytokines, such as IL-6 and TNF-alpha, are believed to influence brain chemistry and mood regulation, playing a key role in the development of depression." (PMID 39727650, 2024). "One previous study (n = 275) which used the NPI to rate neuropsychiatric symptoms reported raised serum TNF-α in individuals with depression." (PMID 39526037, 2024).
depression (continued). "After 24 weeks of HFHSD exposure, male mice showed a general depression in the expression of cytokines, with prominent reduction of TNF-α, IL-6 and IL-13, but increased TGF-β, while female mice showed over-expression of IFN-γ and IL-18." (PMID 39302596, 2024). "Previous studies have consistently observed elevated levels of pro-inflammatory cytokines such as interleukin-1β (IL-1β), IL-6, and tumor necrosis factor-α (TNF-α) in the blood of patients with depression." (PMID 39130643, 2024). "Certain cytokines are elevated in persons with depression as well as RA, including IL-1β, IL-6, and TNF-α." (PMID 38340224, 2024). "This heterogeneity underscores the need for further research and a comprehensive understanding of the complex interplay between TNF-α and depression." (PMID 39273641, 2024). "Together, the results indicated that decreasing TNF levels improved depression-like behaviors in CUMS mice." (PMID 38710713, 2024). "Elevated levels of cytokines like interleukin-6 (IL-6) and tumor necrosis factor-alpha (TNF-alpha) have also been linked to psychological conditions, including mood disorders such as depression and anxiety." (PMID 39618672, 2024). "In conclusion, our data provided new evidence that TNF-α/TNFR1 are crucial players in the process of depression." (PMID 38710713, 2024). "Brexanolone reduced baseline levels of the inflammatory markers TNF-α and IL-6, and these effects predicted improvement in the Hamilton Rating Scale for Depression (HAM-D) scores." (PMID 38792602, 2024). "Furthermore, the dysregulation of serum inflammatory cytokines, such as IL-1β, IL-6, and TNF-α, has been observed in pediatric patients with major depressive disorder (MDD), and it is linked to depression in children with cancer." (PMID 38927907, 2024). "It has been shown to protect against CUMS-induced depression by enhancing the gut microbiome’s reconstruction and reducing inflammation in the colon by downregulating the expression levels of IL-6, IL-1β, and TNF-α." (PMID 39459643, 2024). "Increased levels of pro-inflammatory cytokines in the peripheral circulation, including interleukin (IL)-1β and the tumor necrosis factor alpha (TNF)-α, have been associated with a higher probability of major depressive disorder." (PMID 38473892, 2024). "Third, regardless of symptom severity, bipolar disorder can be distinguished from major depressive disorder based on an elevated TNF-α level and less stable inhibitory control, as was evidenced by the SD of the reaction time in the go/no-go task." (PMID 39283831, 2024). "Elevated levels of pro-inflammatory cytokines (including Tumor Necrosis Factor-alpha (TNF-alpha) and Interleukin 6 (IL-6)) influence brain function, leading to depression, anxiety, and anger in humans." (PMID 39061510, 2024). "Since TNF-α is a vital proinflammatory cytokine in the CNS and different studies have demonstrated its role in depression; we measured the effects of X15856 on gene expression and the protein synthesis of TNF-α in LPS-stimulated BV2 microglial cells." (PMID 38674048, 2024). "A meta-analysis found that levels of IL-6 and TNF are increased in the blood of depression patients." (PMID 39201033, 2024). "In contrast, S-ketamine mitigates IL-1b–induced TNF-a, as well as IL-6–induced IL-1b and IL-8, highlighting the importance of considering ketamine formulation in depression treatment." (PMID 39297528, 2024). "The finding that psychological stress, specifically anxiety and depression in humans, can trigger the release of pro-inflammatory cytokines like TNF-α has significant consequences for the pathology of humans." (PMID 39605919, 2024). "The clinical study has reported that elevated levels of pro-inflammatory cytokines IL-1β, IL-6, and TNF-α are observed in depression patients, accompanied by the activation of microglia in the central nervous system." (PMID 38643466, 2024).
depression (continued). "First, contrary to adults, low blood levels of TNF-α were found both in adolescents with severe depression and suicidal thoughts and in children with dysthymia." (PMID 38586283, 2024). "Clinical studies have suggested a correlation between TNF-α, an activator of A1 astrocytes, and the severity of depression." (PMID 38710713, 2024). "Studies have shown elevated levels of TNF-α receptors in patients with Type D personality and MDD, indicating a possible link between TNF and depression." (PMID 39329797, 2024). "Some pro-inflammatory cytokines such as IL-1, IL-6, and TNF-α, but also corticosteroids and dopamine, play a role in the pathogenesis of depressive disorders in individuals with atopic dermatitis." (PMID 38731996, 2024). "Several studies have shown that the intraperitoneal injection of LPS upregulates the expression of proinflammatory cytokines, including IL-1β, IL-6, and TNF-α, leading to anxiety, depression, and cognitive deficits." (PMID 37560531, 2023). "Further, excessive proinflammatory cytokines release such as MCP-1, IL-1, IL-6, and TNF-alpha leads to behaviors comparable to depression." (PMID 36986674, 2023). "It is suggested that exercise can inhibit proinflammatory factors TNF-α, IL-6, and IL-18 to improve depression." (PMID 37239191, 2023). "In a subset of individuals diagnosed with Major Depression that also have high inflammatory markers, TNFα inhibition reduced depression scores." (PMID 37706039, 2023). "Adolescent ethanol consumption can drive the hyperactivation of microglia in raphe nuclei, leading to increased levels of TNF-α and IL-10, decreased serotonergic activity, and neuropsychiatric consequences of hyperalgesia and depression." (PMID 37794488, 2023). "TNF-α on D1, D3, and D7, IL-8 at baseline, D1, D3, and D7, IL-17A on D1 and D7 correlated with increased depression rate (all P<0.05)." (PMID 37878890, 2023). "Increased inflammatory markers, including CRP, IL-6, TNF-α, and IL-1β, have been reported in patients with depression." (PMID 37511030, 2023). "In contrast, there was a significant increase in the levels of IFN-γ and TNF-α in cancer patients with depression compared to the cancer patients (postrate and breast cancer) alone." (PMID 37153524, 2023). "Various studies have shown that increased levels of TNFα, IL1β and IL 6 are detected in patients with major depression, BD, schizophrenia and other psychiatric diseases." (PMID 36676137, 2023). "It is proposed that IL‐10 is an anti‐inflammatory, immunomodulatory cytokine that is shown to improve neurological injuries like ST and depression and acts against excitotoxicity through the inhibition of TNF‐α synthesis." (PMID 36655100, 2023). "The mixture of Lactobacillus and Bifidobacteium can repress NF‐κB, TNF‐α, and bacterial lipopolysaccharide in depression, showing that there is the potential synergistic effect between the two microbiotas." (PMID 36550591, 2023). "Depression patients were found to have significantly higher levels of TNF-α and CCL2 in the plasma, and increased expression levels of TNF-α together with decreased IL-6, in PBMCs." (PMID 37575572, 2023). "The treatment normalized brain levels of IL-1β, TNFα, and IFNγ which were higher in depression models." (PMID 37240605, 2023). "A second study also found that neurocognitive symptoms in patients with depression were positively correlated with the transcription levels of pro-inflammatory factors TNF-α, IL-16, McP-1, McP-2, MIP-1-α, MIP-1 -β, TGF -β, and IFN-β." (PMID 37270510, 2023). "GP-14 treatment effectively inhibited the increase of pro-inflammatory cytokines, for example, IL-6, IL-1β, and TNF-α, in the serum from mice in the LPS-induced depression model." (PMID 37631068, 2023). "Higher levels of IL-6, NLRP3, and TNF- α predicted a better response to ECT in patients with treatment-resistant depression." (PMID 37699900, 2023).
depression (continued). "Studies on immune inflammation and depression animal models have shown that systemic inflammatory response induced by lipopolysaccharide, tumor necrosis factor α and other pro-inflammatory factors can lead to depression-like behavior in mice." (PMID 37275977, 2023). "Previously, it was reported that increased IL-17, IL-6, and TNF-α (the components of the Th17-axis in the current study) contribute to major depressive disorder and chronic fatigue symptoms." (PMID 37509005, 2023). "Some cytokines, such as IL-1β, IL-6 and tumour necrosis factor-α (TNF-α) appear to be involved in the onset and progression of depression." (PMID 37836393, 2023). "TNF-α and IL-6 are inflammatory indicators and are strongly correlated with postoperative depression." (PMID 37598200, 2023). "In line with this, it was demonstrated that moderate-intensity exercise can lower the proinflammatory cytokine TNF- α blood levels, and reduce depression scores." (PMID 37398548, 2023). "The present results indicated that CLM dramatically decreased the levels of TNF-α and IL-6 in the peripheral blood of patients with depression compared to antidepressant treatment groups." (PMID 37808199, 2023). "In the rat of CUMS model, rTMS treatment significantly improved anxiety and depression-like behavior and reduced the levels of inflammatory factors TNF-α, iNOS, IL-1β, and IL-6 in the hippocampus." (PMID 36624089, 2023). "Our present results showed that long-term EE effectively decreased the expression levels of IL-1β, IL-6, and TNF-α, and improved depression and cognitive deficits in the MSD + EE group compared with those of the MSD group." (PMID 37168717, 2023). "Higher levels of depression symptoms were associated with increased levels of pro-inflammatory biomarkers CRP and TNF-α in older nurses working in the United States." (PMID 37637801, 2023). "On the contrary, the elevated serum levels of IL-1β, IL-6, and TNF-α have been repeatedly observed in major depressive disorder and in bipolar disorder." (PMID 33902760, 2023). "Depression is associated with inflammation by increasing C-reactive protein (CRP) and cytokines, such as interleukin-6 (IL-6) and tumor necrosis factor-α (TNF-α)." (PMID 37096248, 2023). "TNF and NF-B are both components involved in the pathogenicity of depression in depression- and anxiety-induced mice." (PMID 37333479, 2023). "Animal models of depression-like behavior demonstrated elevated proinflammatory cytokine levels, most commonly IL-1 beta and tumor necrosis factor-alpha (TNF-alpha)." (PMID 38067154, 2023). "IL-1β- or TNF-α-knockout mice show reduced levels of anxiety, depression, and cognitive decline relative to that seen in their wild-type counterparts." (PMID 37560531, 2023). "In PBMCs of depression patients, TNF-α and IL-6 expression levels were significantly up and downregulated, respectively." (PMID 37575572, 2023). "In conclusion, exercise can improve depression by inhibiting inflammatory factors (e.g., TNF-α, IL-6, and IL-18) and promoting anti-inflammatory factor TGF-β1, inhibiting the inflammatory response." (PMID 37239191, 2023). "Previous research has demonstrated that major depressive disorder patients are in a proinflammatory state, with elevated levels of innate immune plasma mediators such as IL-6, TNF-a, and C-reactive protein." (PMID 37924045, 2023). "The probiotic combination reduced depression, anxiety scores, and circulating levels of TNFα, as well as improving sleep quality." (PMID 36178333, 2023). "The high levels of inflammatory cytokines such as TGF-β, TNF-α, and IL-1β in the peripheral blood of patients with depression fully indicate that inflammation is related to depression." (PMID 37868345, 2023). "The concentrations of proinflammatory cytokines (TNF-α and IL-2) have been found to correlate with depression severity." (PMID 37834806, 2023).